IGF2R (insulin like growth factor 2 receptor)
Diseases named in the same sentence as IGF2R in open-access papers (continued):
Sharing a sentence is not in itself a finding about the gene and the disease.
tumor (continued). "In the present case, the tumor expressed both IGF2 and IGF2R; however, IGFR1 was unexpectedly downregulated." (PMID 30168002, 2018). "Results of IHC staining were obtained for 285 (98.6%) of tumor samples for all three markers (IGF1R-alpha, IGF1R-beta and IGF2R)." (PMID 23365645, 2013). "The mRNA level of IGF-1, IGF-1R, IGF-2, IGF-2R, and IGFBP-3 was significantly higher in tumor and tumor-adjacent endometrium than that in control endometrium (p < 0.05)." (PMID 22720981, 2012). "IGF-2R and IGFBP-2 were then used to differentiate between tumor samples and matching paratumorous samples using unsupervised hierarchical cluster analysis." (PMID 23071652, 2012). "Two out of 10 proteins (IGF-2R and IGFBP-2) were differentially expressed between tumor samples and matching paratumorous samples, with P-values of less than 0.05." (PMID 23071652, 2012). "We further study the correlation of IGF-1, IGF-1R, IGF-2, IGF-2R, and IGFBP-3 mRNA expression with ERα and ERβ mRNA expression in tumor, tumor-adjacent and control endometria." (PMID 22720981, 2012). "The tumor endometrium expressed significantly lower levels of IGF-1, IGF-1R, and IGF-2, and significantly higher levels of IGF-2R and IGFBP-3, compared with tumor-adjacent endometrium (p < 0.05)." (PMID 22720981, 2012). "We tested the expression of IGF-1, IGF-1R, IGF-2, IGF-2R, IGFBP-3, ERα and ERβ mRNA on 58 tumor tissue samples and 31 tumor-adjacent endometrial tissue samples from patients with EAC and 42 normal endometrial tissue samples, using RT-PCR." (PMID 22720981, 2012). "Other findings reflective of CS1’s higher tumor grade and more aggressive behavior compared with CDS11 cells include the significantly higher mRNA levels of INSULINR, IGF2R, IRS1, NOTCH1, JAGGED1, HES1, and HIF1α, which function to promote tumor cell growth and survival." (PMID 40427168, 2025). "Insulin-like growth factor 2 receptor (IGF2R) is overexpressed in OS, which has been used to develop radiolabeled antibody targeting IGF2R with Indium-111, Lutetium-177 and Bismuth-213 and showing delayed tumor growth in vivo in an OS model." (PMID 35884563, 2022). "The radioimmunotherapy (RIT) of OS tumors with IGF2R-specific mAbs MEM-238 and 2G11, which are 188Rhenium-labeled (188Re-labeled) and 177Lutetium-labeled (177Lu-labeled), respectively, resulted in tumor growth inhibition and even regression in some mice, with acceptable safety." (PMID 35056067, 2021). "Our previous work demonstrated the preferential tumor localization of the radiolabeled monoclonal antibodies (mAbs) to human IGF2R (mAb MEM-238) and to human and murine IGF2R (mAb 2G11) in OS xenografts and patients derived xenografts (PDX) in mice in comparison with the control mAbs." (PMID 34064450, 2021). "Biodistribution and microSPECT/CT imaging reveal selective uptake of the radiolabeled IGF2R-specific mAb 2G11 within the tumor as well as the spleen, with the latter resulting in no detectable untoward effect within the experimental time course." (PMID 31391495, 2019). "We previously reported that GSE down-regulated the miR-17-92 cluster host gene (MIR17HG) and miR-19a/b in various NSCLC (A549, H520, H1299) and bronchial premalignant cancer cells, leading to up-regulations of their downstream targets - tumor suppressors PTEN and IGF2R." (PMID 29643994, 2018). "The present results indicate that the tumor co-expressed IGF2 and IGF2R." (PMID 30168002, 2018). "In particular, IGFBPs and IGF2R provide two separate mechanisms to regulate IGF2 bioavailability and have each been suggested as a potential tumor suppressor; however, it remains unclear which plays the dominant role in regulating IGF2 activity in tumors." (PMID 26861122, 2016). "IGF-2R serves as a sink to IGF-2R and does not allow the signal transduction of the latter and has the characteristics of a tumour suppressor which is discussed in previous section on targeting IGF-Rs." (PMID 25866791, 2015).
tumor (continued). "Whether or not IGF2R inhibits the recruitment of TILs through some pathways or cytokines and whether it promotes the depletion of TILs in the tumor might be a direction for future research related to TNBC." (PMID 36330486, 2022). "Moreover, EGFR-mutated NSCLC cells with high TROP2 expression developed more rapid resistance to gefitinib therapy through the interaction of TROP2 with insulin-like growth factor 2 receptor (IGF2R), the induction of AKT, and the remodeling of the tumor microenvironment." (PMID 36077674, 2022). "Notably, authors proposed that in those HCAs associated with an increase in insulin-like growth factor 2 (IGF2) by inactivation of the insulin-like growth factor 2 receptor (IGF2R) gene, a therapy targeting IGF2 could effectively prevent tumor malignancy." (PMID 33922238, 2021). "The tumor cells were positive for IGF2R but negative for IGF1R." (PMID 30168002, 2018). "Although IGF1R was not expressed in the tumor, IGF2R was overexpressed." (PMID 30168002, 2018). "IGF2R also has a high affinity for IGF ligands, particularly IGF2; however, the receptor lacks an intracellular tyrosine kinase domain that is essential for the activation of the IGF pathway, thus, the receptor acts as a “decoy” of the IGF pathway and is recognized as a tumor suppressor gene." (PMID 30373548, 2018). "CD49E/ITGA5 and CD222/IGF2R were prognostic in the same direction in both SQCCs and ADCs, suggesting that despite elevated expression in SQCCs, these proteins may perform similar functions in the two tumor types and their cells of origin." (PMID 25551685, 2014). "In this context, the initially described tumor-suppressive and anti-invasive properties of TRPM1 have recently been shown to be executed by its intronic miR-211 (and not by TRPM1 itself) via down-regulation of the miR-211 direct and indirect targets TGFBR2, NFAT5, and IGF2R." (PMID 24039954, 2013). "Interestingly, in vitro 143B cells expressed approximately 2 times more IGF2R than OS-17 cells, whereas in vivo the uptake of IGF2R-binding 2G11 mAb into the tumors was similar for both cells lines, with the tumor uptake being even slightly higher, though not significantly, in OS-17 tumors." (PMID 31391495, 2019). "In addition, the tumor expressed IGF2 receptor (IGF2R) but not IGF1R." (PMID 30168002, 2018). "Although there are two receptors for IGFs, IGF-1R and IGF-2R, IGF-2R does not transduce a signal and acts to reduce the bioavailability of IGF-2 by sequestering it away from IGF-1R and thus acts as a tumor suppressor." (PMID 24885964, 2014). "Here, we show that this is restricted to tumours expressing high levels of IGF1R, IGF2R or HER2, whereas no prognostic significance could be seen in the IGFR/HER2 negative group." (PMID 26698305, 2015).
cancer (67 papers, 2010 to 2025). A tumor composed of atypical neoplastic, often pleomorphic cells that invade other tissues. "Perturbation in IGF2/IGF2R signaling has been associated with autophagy impairment in several human diseases (such as Parkinson’s disease and cancer) and similar evidence has been observed in mice brains after treatment with IGF2." (PMID 38612397, 2024). "The dysregulation of IGF2R has been associated with several diseases, including cancer, metabolic disorders, and neurodegenerative diseases." (PMID 38255751, 2024). "IGF2 binding activates IGF1R and IGF2R and is associated with aberrant glucose metabolism and proteoglycan dysregulation, which is responsible for cancer development." (PMID 35391781, 2022). "Lately, it has been shown that the IGF axis with an emphasis on the IGF2R gene is responsible for metastatic niche formation by transforming the normal fibroblast into cancer-associated fibroblasts (CAFs)." (PMID 34571863, 2021). "IGF2/IGF2R interaction influences cell growth, survival, and migration in normal tissue development, and the deregulation of IGF2R expression has been associated with growth-related disease and cancer." (PMID 32075092, 2020). "Genetic mutations in IGF2R can modify the bioavailability of IGF2 so that cancer cells can dramatically proliferate." (PMID 32075092, 2020). "Mutation and loss of heterozygosity of IGF2R occurs in human cancers, including the mutation I1572A in domain 1128,33–36." (PMID 31388182, 2019). "MM was significantly associated with IGF2R mutations, which are relatively low in other cancer types from TCGA database, indicating the unique genetic background of MM." (PMID 30373548, 2018). "In the development of cancer, defects in IGF-2R are reportedly caused by loss of imprinting." (PMID 37834454, 2023). "For example, we lack models to investigate germ-line non-synonymous IGF2R polymorphisms that occur in humans and the somatic loss of function mutations that detected in common human cancers, with the latter frequently co-existing with loss of heterozygosity of IGF2R.." (PMID 23468951, 2013). "This topic merits further investigation because preclinical studies have shown that several cancers expressing high levels of IGF-2 due to IGF-2R mutation and loss of heterozygosity (LOH) are more responsive to both anti-IGF-1R antibodies and anti-sense directed against IGF-2 or IGF-1R." (PMID 22022506, 2011). "Mutations in IGF-2R have been found in many types of cancer (see Discussion), and may predict response to IGF-1R inhibitors." (PMID 22022506, 2011). "IGF2R deletion or mutation may contribute to the development and progression of cancer." (PMID 36330486, 2022). "Moreover, the association of IGF2R/IGF2 with cancer progression appears controversial." (PMID 30168002, 2018). "Notably, the frequency of IGF2R mutations were higher than other cancer types from TCGA database." (PMID 30373548, 2018). "However, some cancer-associated M6P/IGF2R mutations have beenfound to reduce M6P binding." (PMID 23347038, 2013). "To analyze the allelic expression of imprinted genes in cancer, we selected 5 imprinted genes GNAS, GRB10, SNRPN, IGF2, and IGF2R which were mostly reported to be associated with cancer." (PMID 32448196, 2020). "IGF2 and IGF2R are usually referred in the studies on imprinted genes and cancers, which we have also tested in our samples." (PMID 32448196, 2020). "In our analysis, we found that seven out of 10 pedigrees had potential co-segregated pathogenic variants in known cancer-associated genes, including CHEK2, ATM, MRE11, and CTR9, and some other cancer-associated genes, such as IGF2R and CHRNA3." (PMID 31214250, 2019). "In some cancers, high frequencies of loss-of-heterozygosity (LOH) at the IGF2R locus have been reported." (PMID 31748500, 2019).
cancer (continued). "Although IGF2/IGF1R and IGF2/IR complexes primarily activate intracellular signal transduction for cell proliferation, some studies have reported that IGF2/IGF2R complex plays a role in cancer progression." (PMID 30168002, 2018). "Here, we found mutated genes at the level of the receptor itself in 7% of cases: focal amplification of IGF1R (n=3) and of IGF1 (n=2); frameshift indels in the recessive cancer genes, IGF2R (n=2) and IGFBP5 (n=1)." (PMID 28643781, 2017). "Silencing IGF-2 or STAT3 expression in cancer cells or IGF-2R or CXCL8 expression in stromal cells significantly inhibits the cancer–stroma communication and vascular endothelial cells' angiogenic activities." (PMID 26465273, 2015). "IGF-1R can be founded in most solid tumors and hematological malignancies examined to date, and IGF-2 overexpression, IGFBP modulations, and IGF-2R down-regulation have also been founded in cancer cells." (PMID 25424625, 2014). "It is currently believed that the functions of M6P/IGF2R in development and cancer suppressionrely mainly on its ability to control the biological activities of IGF-II." (PMID 23347038, 2013). "These two cases presented also alterations in the BAX and IGF2R genes in their carcinomas, which are compatible with a constitutional MMR deficiency that leads to an acquired genetic instability." (PMID 20979647, 2010). "In addition, in cancer cell lines, a dysregulation of autophagic function and reduced degradative capacity of lysosomes following IGF2R knockdown has been observed." (PMID 38612397, 2024). "Studies showing prognostic impact of altered expression of IGF-2R in various cancer types." (PMID 37834454, 2023). "The insulin-like growth factor receptor type 2 (IGF2R) sequesters the insulin-like growth factor (IGF-II) for internalization and degradation and also is considered a tumor suppressor with mutations being found in several cancers." (PMID 36768202, 2023). "Here, we evaluate Igf2r specific loss-of-function of the domain-11 IGF2 binding site by replacing isoleucine with alanine in the CD loop (exon 34, I1565A), a mutation also detected in cancers." (PMID 31388182, 2019). "Therefore, the role of the IGF2/IGF2R complex in cancer progression should be investigated in further studies." (PMID 30168002, 2018). "However, an in vitro study revealed that IGF2R knockdown significantly reduced IGF2-related ERK1/2 phosphorylation, suggesting that the complex of IGF2 and IGF2R participates in cancer cell proliferation." (PMID 30168002, 2018). "IGF2R is mutated frequently in LUSC and it suppresses cancer cell growth." (PMID 29484121, 2018). "Therefore, to analyze the relative role of IGFBPs and IGF2R in cancer, we developed a mass-action kinetics model of the IGF network that incorporated IGF1, IGF2, IGF1R, IGF2R, and IGFBPs." (PMID 26861122, 2016). "We propose that this mechanism may be leveraged for the treatment of cancers by exploiting the M6P/IGF2R-mediated destruction of IGF-II to inhibit progression of IGF-II-dependent tumors." (PMID 27694692, 2016). "We therefore assessed the role of IGF-2 and IGF-2R in cancer–stroma communication." (PMID 26465273, 2015). "The CM from cixutumumab-treated cancer cells failed to increase CXCL8 transcripts in Wi38 cells with an shRNA-mediated loss of IGF-2R expression and also in cells that had been incubated with neutralizing antibody blocking IGF-2R." (PMID 26465273, 2015). "Thus lackof functional M6P/IGF2R expression possibly favours cancer outgrowth and metastasis largely byenhancing the release of M6P-modified proteins such as lysosomal proteinases and/or other acidhydrolases into the extracellular space." (PMID 23347038, 2013). "CD222/ insulin-like growth factor-2 (IGF2R) has long been recognized as a cancer-expressed protein." (PMID 23251904, 2012). "Therefore, we examined whether Trop2 binding IGF2R functions in drug resistance within the crosstalk between infiltrating stromal cells and gefitinib resistant cancer cells." (PMID 34335947, 2021).
cancer (continued). "Also, the cluster with IGF1R and IGF2R in module 4 may also be useful for prognostic biomarkers in five cancers." (PMID 28676692, 2017). "However, recent findings suggest that the IGF2R may trigger a signalling cascade leading to cardiac muscle cell hypertrophy, the regulation of cell invasion and cell motility in human cancer cells and the binding of multiple ligands other than IGF-II." (PMID 20559434, 2010). "The study aims to provide fundamental descriptive data for IGF2R expression for future evaluation of RIT in the treatment of canine and human OS and potentially other cancers." (PMID 36768202, 2023). "We found that Trop2 physically interacted with IGF2R and resulted in cytokine production, TME remodeling, recruitment of infiltrated macrophages, and the proliferation of cancer cells." (PMID 34335947, 2021). "Using these results, imprinted genes GNAS, GRB10, and SNRPN were identified as the more efficient cancer biomarkers over IGF2 and IGF2R, specifically using our QCIGISH method." (PMID 32448196, 2020). "IGF2R inhibition in NSCLC cell lines resulted in increased proliferation, migration and invasion abilities and a reduced apoptosis rate of the cancer cells." (PMID 29484121, 2018). "Thus, an attractive hypothesis is that increased epithelial IGF-2 production leads to macrophage and fibroblast chemotaxis, which subsequently stimulates CXCL8 expression in stromal cells through the IG-F2/IGF-2R axis, resulting in endothelial cell recruitment and cancer cell migration." (PMID 26465273, 2015). "In conclusion, our data identify anti-IGF-1R monoclonal antibody-induced cancer–stromal cell communication via STAT3-dependent IGF-2 production in cancer cells and a positive IGF-2/CXCL8 feedback loop through the intercellular IGF-2/IGF-2R system." (PMID 26465273, 2015). "Analysis of data from The Cancer Genome Atlas (TCGA) using the cBIO portal across most cancer types shows genomic alterations in IGF ligands (IGF1, 2), receptors (IGF1R, IGF2R), binding proteins (IGFBP1–6), and IRSs (IRS1, 2, 4); this representing 18 genes." (PMID 25964777, 2015). "Indeed, the expression of IGF1R, IGF2R, FGFR2-4, and de novo fatty acid biosynthetic enzymes (ACC1, FASN) correlates with ferroptosis resistance across 824 primary, adherent cancer cell lines." (PMID 40000627, 2025). "Although IGF2 and IGF2R genes were also observed to be related to cancer, they were not the best biomarkers specifically using our QCIGISH method." (PMID 32448196, 2020). "In order to find useful and efficient cancer biomarkers for clinical applications, we generated the ROC curves for the GNAS, GRB10, SNRPN, IGF2, and IGF2R imprinted genes using the individual BAE, MAE, and TE measurements for all the different cancer types combined." (PMID 32448196, 2020). "Cixutumumab treatment stimulates STAT3-dependent transcriptional upregulation of IGF-2 in cancer cells and recruitment of macrophages and fibroblasts via paracrine IGF-2/IGF-2R activation, resulting in the stroma-derived CXCL8 production, and thus angiogenic and metastatic environment." (PMID 26465273, 2015). "Mutations in the MSI target genes IGF2R and BAX were found in one (33.3%) and two (66.7%) out of the three rectal MSI-H carcinomas, respectively, whereas no mutations were detected in TGFBR2, MSH3, and MSH6 microsatellite sequences in this test series." (PMID 20979647, 2010). "This parallel increase in IGF2 transcription, coupled with defective cancer processing, generates the known high-molecular IGF-II pro-hormone variants, which are refractive to IGFBP-3 (and SpI2-6/IGF2R) binding but not to the IGF-II RTKs (IGF-IR and IRA) which are efficiently activated." (PMID 38255147, 2023).
cancer (continued). "Thus, in some cancers, IGF2R may behave not as a tumor suppressor gene but as an oncogene." (PMID 31748500, 2019). "Interestingly, the low rather than high levels of CSNK1E, IGF2R, IRAK3, and PRKAA1 relate to poor cancer prognosis, suggesting that kinases often play a divergent role in different types of cancer." (PMID 26956052, 2016). "In contrast to our analysis, a prior model of this system in cartilage suggested the IGF2R might play a role in regulating IGF2 interactions with IGF1R; however, these findings were not confirmed experimentally and were not seen in our model utilizing data from cancer cells." (PMID 26861122, 2016).